PLCB4 (phospholipase C beta 4)
Description:
Activated phosphatidylinositol-specific phospholipase C enzymes catalyze the production of the second messenger molecules diacylglycerol (DAG) and inositol 1,4,5-trisphosphate (IP3) involved in G protein-coupled receptor signaling pathways. PLCB4 is a direct effector of the endothelin receptor signaling pathway that plays an essential role in lower jaw and middle ear structures development.
Synonyms: ARCND2; ARCND2A; ARCND2B; PI-PLC
Tractability: Antibody: UniProt places it where antibodies can reach, with high confidence; its Gene Ontology location is reachable by antibodies, with high confidence. PROTAC: ubiquitination databases record sites on it; its protein half-life has been measured.
Gene: Protein-coding gene on chromosome 20 (9,067,825 to 9,504,593, forward strand). Ensembl gene ENSG00000101333.
Subcellular location: Cell membrane
Subcellular location (Human Protein Atlas): Basal body; Microtubules; Plasma membrane; Primary cilium; Acrosome; Actin filaments; Centrosome; Cytokinetic bridge; End piece; Equatorial segment; Mid piece; Nucleoplasm; Principal piece
Pathways (Reactome):
Signal Transduction: G alpha (q) signalling events; PLC beta mediated events
Metabolism: Synthesis of IP3 and IP4 in the cytosol
Gene Ontology:
Molecular function: protein binding; phosphatidylinositol phospholipase C activity; phosphatidylinositol-4,5-bisphosphate phospholipase C activity; phospholipase C activity; calcium ion binding; phosphoric diester hydrolase activity
Biological process: phospholipase C-activating endothelin receptor signaling pathway; G protein-coupled receptor signaling pathway; phosphatidylinositol metabolic process; phosphatidylinositol-mediated signaling; release of sequestered calcium ion into cytosol; intracellular signal transduction; lipid catabolic process; lipid metabolic process; signal transduction
Cellular component: plasma membrane; cytosol
Genetic constraint (gnomAD): Loss-of-function variants: 15 observed, 45.4 expected, observed/expected ratio (o/e) 0.33, 90% interval 0.22 to 0.51. The upper end of that interval is the gene's LOEUF score, 0.51, which puts it in group 2 of 6, group 1 being the genes least tolerant of losing a copy. Missense variants: 338 observed, 548.58 expected, observed/expected ratio (o/e) 0.62, 90% interval 0.56 to 0.67. Synonymous variants: 190 observed, 195 expected, observed/expected ratio (o/e) 0.97, 90% interval 0.87 to 1.1.
Gene-disease validity (ClinGen):
ClinGen rates the evidence that PLCB4 causes each of these diseases.
auriculocondylar syndrome 2 (autosomal dominant; autosomal recessive): Definitive.
Homologues: Orthologues: chimpanzee PLCB4 (99% identical), macaque PLCB4 (99% identical), rat Plcb4 (98% identical), dog PLCB4 (98% identical), guinea pig PLCB4 (97% identical), pig PLCB4 (95% identical), mouse Plcb4 (94% identical), rabbit PLCB4 (92% identical), tropical clawed frog plcb4 (87% identical), zebrafish PLCB4 (68% identical), Drosophila melanogaster norpA (50% identical), Caenorhabditis elegans egl-8 (49% identical). Paralogues in human: PLCB1 (39% identical), PLCB3 (37% identical), PLCB2 (34% identical), PLCE1 (25% identical), PLCH1 (24% identical), PLCH2 (23% identical), PLCL2 (22% identical), PLCL1 (22% identical), PLCD4 (21% identical), PLCG1 (20% identical), PLCD1 (20% identical), PLCD3 (20% identical), and 2 more.
Diseases named in the same sentence as PLCB4 in open-access papers:
PLCB4 is named in the same sentence as 62 diseases in open-access papers, as found by Europe PMC text mining. Sharing a sentence is not in itself a finding about the gene and the disease. The quoted sentences say what the papers report.
uveal melanoma (13 papers, 2016 to 2025). A melanoma derived from melanocytes of the uveal tract. "Their effect has not been precisely studied, but their exclusivity with the GNAQ, GNA11, and CYSLTR2 mutations and PLCβ4 being downstream of these proteins suggest that PLCβ4 mutations have a similar effect on the oncogenicity of uveal melanomas." (PMID 35158973, 2022). "PLCB4 mutations occur in approximately 5% of uveal melanoma and are mutually exclusive with GNAQ, GNA11, and CYSLTR2 mutations." (PMID 35158973, 2022). "The essential role of Gαq signalling in uveal melanoma tumorigenesis has been further supported by the discovery of rare but recurrent mutations in PLCB4 (p.D630) and CYSLTR2 (p.L129Q)." (PMID 33588787, 2021). "In the TCGA cohort, mutations in GNAQ/11, CYSLTR2, and PLCB4 (2.5%) were found in 92.5%, 4%, and 2.5% of the samples, respectively, highlighting the involvement of G-protein signaling in the biology of uveal melanoma." (PMID 31357599, 2019). "The first mutation set encompasses the eight UM driver genes according to the TCGA study, divided into “uveal melanoma initiating mutations” (CYSLTR2, GNA11, GNAQ and PLCB4) and “second hit mutations with prognostic impact” (BAP1, EIF1AX, SF3B1 and SRSF2)." (PMID 39858540, 2025). "In uveal melanoma, PLCB4 mediates complex downstream signaling cascades triggered by upstream driver mutations, contributing to tumors with diverse genetic and signaling characteristics." (PMID 40852729, 2025). "The potential role of wild-type CYSLTR2 in GNAQ, GNA11 or PLCB4 mutant uveal melanomas was studied in publicly available bulk and single cell sequencing data." (PMID 33588787, 2021). "Uveal melanoma (UM) has well-characterised somatic copy number alterations (SCNA) in chromosomes 1, 3, 6 and 8, in addition to mutations in GNAQ, GNA11, CYSLTR2, PLCB4, BAP1, SF3B1 and EIF1AX, most being linked to metastatic-risk." (PMID 32340176, 2020). "Among Uveal Melanoma (UM) driver mutations, those involving GNAQ or GNA11 genes are the most frequent, while a minor fraction of tumors bears mutations in the PLCB4 or CYSLTR2 genes." (PMID 31216772, 2019). "In one vfDNA+/UM− patient, the primary uveal melanoma was known to carry two clonally-abundant Gαq signalling mutations (GNA11 p.R183H and PLCB4 p.D630N in vfDNA-29), but the vfDNA only contained wild-type GNA11 and PLCB4 in comparable concentrations." (PMID 40240901, 2025). "A total of 99 of these 118 patients (84%) had detectable ctDNA at baseline and on treatment, of whom 94 had mutations detected in one or more uveal melanoma genes (GNAQ, GNA11, SF3B1, PLCB4, CYSLTR2) at a variant allelic frequency of >0.3 at baseline and were included in the analyses." (PMID 36229663, 2022). "Another recent study reported the recurrent mutation in PLCB4, occurring in about 4% of uveal melanomas; importantly, PLCB4D630Y mutations are mutually exclusive with mutations in GNA11 and GNAQ, in line with the observation that PLCB4 is a canonical downstream target of GNA genes." (PMID 29156643, 2017). "Expansion into publicly available bulk and single cell uveal melanoma sequencing data allowed to evaluate our findings in independent cohorts of primary and metastatic tumours and to study the role of wild-type CYSLTR2 in melanomas with a mutation in GNAQ, GNA11 or PLCB4." (PMID 33588787, 2021). "Thus, GNAQ, GNA11, PLCB4, and CYSLTR2 form four modules of independent mutated uveal melanomas." (PMID 29156643, 2017). "Tumors that did not harbor these mutations were found to have mutations in CYSLTR2, a G-protein-coupled receptor, in 4% of samples and in PLCB4, a downstream effector of GNAQ signaling in 2.5% of samples, highlighting the involvement of G-protein signaling in the biology of uveal melanoma." (PMID 31357599, 2019).
uveal melanoma (continued). "A recent study reported recurrent mutations of G-protein-coupled receptor CYSLTR2 (cysteinyl leokotriene receptor 2) exclusively occurring in uveal melanoma patients not displaying GNAQ, GNA11, and phospholipase C, beta 4 (PLCB4) mutations (in about 40% of these patients)." (PMID 29156643, 2017).
melanoma (10 papers, 2017 to 2025). A malignant, usually aggressive tumor composed of atypical, neoplastic melanocytes. "All these melanomas were wild-type for CYSLTR2 and the majority carried mutations in GNAQ, GNA11 or PLCB4." (PMID 33588787, 2021). "Boosted expression of PLCB4 is correlated with a decrease in survival rates in patients with solid tumors, including mesothelioma, melanoma, and gastrointestinal tumors." (PMID 34552929, 2021). "Hence, gain-of-function mutations in GNAQ, GNA11, or PLCB4 only drive melanoma in melanocytes surrounded by mesenchymal stromas, and not by keratinocytes." (PMID 34939927, 2021). "In exceedingly difficult cases, molecular and genomic analysis can also be beneficial, as melanoma arising in blue nevi do not typically exhibit BRAF mutations, but rather GNAQ, GNA11, PLCB4, or CYSLTR2 mutations." (PMID 40843873, 2025).
auriculocondylar syndrome (9 papers, 2016 to 2025). Auriculo-condylar syndrome (ACS) presents with bilateral external ear malformations ('question mark' ears), mandibular condyle hypoplasia, microstomia, micrognathia, microglossia and facial asymmetry. "Furthermore, mutations in PLCβ4 are associated with a human disease known as auriculocondylar syndrome, also referred to as question-mark ear syndrome, in which patients have developmental defects in their ears and mandible." (PMID 39894822, 2025). "Recessive and dominant mutations in PLCB4 cause auriculocondylar syndrome 2 (OMIM 614669)." (PMID 38300321, 2024). "Auriculocondylar syndrome 2 (ARCND2) is a rare autosomal dominant craniofacial malformation syndrome linked to multiple genetic variants in the coding sequence of phospholipase C β4 (PLCB4)." (PMID 35284927, 2022). "Germline pathogenic variants in GNA11 are also associated with dominantly inherited hypo‐ and hypercalcemia, while those in PLCB4 with dominantly and recessively inherited auriculocondylar syndrome." (PMID 39344744, 2025). "Genetic variants in PLCB4 have been identified as cause of the Auriculocondylar syndrome 2 (ARCND2), a disease characterized by craniofacial malformations, PLCB4 acts as a direct signaling effector of the endothelin receptor type A (EDNRA)-Gq/11 pathway." (PMID 38715801, 2024). "PLCB4, EDN, and EDNRA are closely related to human auriculocondylar syndrome (ACS, MIM #614669, #602483, #615706), which shares similar phenotypes with OAVS like ear and mandibular deformities, suggesting a functional link with ITPR1." (PMID 33747042, 2021).
Ataxia (5 papers, 2012 to 2024). Ataxia refers to impaired coordination of voluntary muscle movement. "The pathway related to growth factors (FGF4, FGF22, and PDGFD), RTK, and PLCB4 was also associated with visual processing defects, ataxia, absence seizures, epilepsy, and Huntington's disease." (PMID 36457060, 2022). "In contrast, moonwalker mutant mice (Trpc–/–) are characterized by severe ataxia attributed to loss of type II UBCs (mGluR1α+ and PLCβ4+) as well as Purkinje cell dysmorphism and loss." (PMID 33488348, 2020). "Plcb4–/– mutant mice exhibited cerebellar hypoplasia and ataxia, closely mirroring neuronal phenotypes associated with IPTR1 mutations, indicating a functional connection between IPTR1 and PLCB1." (PMID 33747042, 2021). "PLCβ4-KO mice show severe cerebellar phenotypes, similar to those shown by mGluR1-KO mice, such as persistent innervation of PCs by multiple climbing fibers, impaired long-term depression at parallel fiber–PC synapses, and severe ataxia." (PMID 38433862, 2024). "Consistent with this notion, Plcb4 mutation in mice can cause ataxia, but human patients, diagnosed with ACS, showed no sign of ataxia." (PMID 33747042, 2021). "The homozygous mouse knockout of a third gene, Plcb4 induces ataxia, although no human patients have been identified with mutations in this gene." (PMID 23028291, 2012).
colorectal cancer (4 papers, 2018 to 2025). A primary or metastatic malignant neoplasm that affects the colon or rectum. "In colorectal cancer, low PLCB4 expression has been associated with poorer patient survival, suggesting its potential as a novel therapeutic target." (PMID 40852729, 2025). "Changes in PLCB4 expression are associated with a decline in survival rates in patients with solid tumors, including mesothelioma, colorectal cancer, and gastrointestinal tumors." (PMID 40027133, 2025).
mesothelioma (4 papers, 2018 to 2025). A usually malignant and aggressive neoplasm of the mesothelium which is often associated with exposure to asbestos. "In mesothelioma cells, activated YAP/TAZ enhances the transcription of a several important genes to stimulate cancer-promotion and progression, such as those encoding connective tissue growth factor (CTGF), phospholipase-C beta 4 (PLCB4), and interleukin 1β (IL1B)." (PMID 37180489, 2023).
osteoporosis (4 papers, 2021 to 2025). A condition of reduced bone mass, with decreased cortical thickness and a decrease in the number and size of the trabeculae of cancellous bone (but normal chemical composition), resulting in increased fracture incidence. "A novel SNP rs6086746 in the PLCB4 promoter was identified to be associated with osteoporosis in Chinese populations." (PMID 34899595, 2021). "Next, we determined the expression of RUNX2 and PLCB4 in osteopenia/osteoporosis patients and controls with different rs6086746 alleles." (PMID 34899595, 2021). "In summary, our data demonstrated that rs6086746 plays an important role in postmenopausal women with osteoporosis susceptibility, modulating the epigenetic regulation of a critical osteoporosis-related gene, PLCB4." (PMID 34899595, 2021). "In this study, we found that the rs6086746 may affect the binding of the RUNX2 transcription factor to increase PLCB4 expression, thereby increasing the risk of osteoporosis." (PMID 34899595, 2021). "We further studied the mechanism underlying osteoporosis regulation by PLCB4." (PMID 34899595, 2021). "Given PLCB4’s role in calcium signaling, essential for osteoblast function, understanding its modulation across populations can inform more tailored osteoporosis therapies." (PMID 40411668, 2025). "Only one study in the Chinese population reported that carriers of the A alleles of the rs6086746 variant in PLCB4, showed a decrease in BMD and an increased risk of developing osteoporosis." (PMID 38715801, 2024). "However, the impact of the RUNX2 binding site SNP rs6086746 and PLCB4 on the development and function of osteoporosis remains incompletely understood, and further exploration of the regulatory mechanism is warranted." (PMID 34899595, 2021). "Therefore, we examined the mRNA levels of RUNX2 and PLCB4 in whole blood extracted from 5 osteopenia patients, 4 osteoporosis patients and 4 controls." (PMID 34899595, 2021). "Thus, our findings reveal that PLCβ4 controls osteoclastogenesis via the RANKL-dependent MKK3–p38 MAPK pathway and that PLCβ4 may be a potential therapeutic candidate for bone diseases such as osteoporosis." (PMID 39894822, 2025). "However, to date, there has been no study that examined the correlation between PLCB4 and osteoporosis, and the related pathogenesis remains unclear." (PMID 34899595, 2021).
Anxiety (3 papers, 2021 to 2022). Intense feelings of nervousness, tension, or panic often arise in response to interpersonal stresses. "The intramodular network of Arap2 also included Plcβ4 and Rora, whose functional expression was associated with improvement in anxiety and depressive symptoms." (PMID 34848858, 2022). "These genes are also associated with anxiety; medial septal Plcb4 knockout mice exhibited more anxiety-like behaviors." (PMID 34276303, 2021). "PlcB4 and NOS1 were expressed at a high level in the medial septum and the hippocampus (two anxiety behavior-related regions), respectively, and inhibition of these genes in the regions with high levels of expression increased anxiolytic effects in a mouse model." (PMID 34763096, 2022).
coronary artery aneurysm (3 papers, 2015 to 2021). "rs6140791 polymorphism of the PLCB4 and PLCB1 genes might be involved in the pathogenesis of coronary artery aneurysm in Kawasaki disease." (PMID 34899595, 2021).
autism (2 papers, 2015 to 2019). Persistent deficits in social interaction and communication and interaction as well as a markedly restricted repertoire of activity and interest as well as repetitive patterns of behavior. "In a screen of 135 genes in the adult mouse (selected for high cerebellar expression or prior association with autism), we identified only three (Abhd3, Lrp8, and Plcβ4) with a somewhat similar lobular expression pattern to Spry3, and none that recapitulated the p75NTR expression pattern." (PMID 31275178, 2019).
colon cancer (2 papers, 2021 to 2023). "Among the 25 predicted miRNAs in this study, high expression of hsa-miR-1271-5p, which was predicted to target PLCB4, was associated with poor OS of colon cancer patients." (PMID 36927770, 2023). "High hsa-miR-1271-5p expression, which may target PLCB4, was significantly associated with poor OS, but the other 24 miRNAs were not significantly correlated with the OS of colon cancer patients." (PMID 36927770, 2023).
epilepsy (2 papers, 2022). A brain disorder characterized by episodes of abnormally increased neuronal discharge resulting in transient episodes of sensory or motor neurological dysfunction, or psychic dysfunction. "Interestingly, regional differences in phospholipase C isoenzyme (Plcb1, Plcb4), druggable targets identified in the Camk2a proteome, expression in the brain are known to underlie several brain disorders including epilepsy, schizophrenia, and AD47." (PMID 35614064, 2022).
glioblastoma (2 papers, 2016 to 2017). The most malignant astrocytic tumor (WHO grade IV). "Recently, an in silico study on glioblastomas indicated significant links between perturbed phosphoinositide metabolism and the CNAs of PLC isoenzymes-encoding genes, including amplified PLCB4 among others." (PMID 28212550, 2017). "Amplifications of PLCB4 were described in glioblastoma multiforme and altered expression was reported in non-small cell lung cancer and endometrial cancer." (PMID 27026853, 2016).
pancreatic ductal adenocarcinoma (2 papers, 2022 to 2025). An infiltrating adenocarcinoma that arises from the epithelial cells of the pancreas. "Integrated multi-omics analyses in pancreatic ductal adenocarcinoma revealed a significant correlation between PLCB4 mRNA expression and gene copy number variation, with tumors exhibiting both intra- and inter-tumoral heterogeneity in CNV patterns." (PMID 40852729, 2025). "By analysing PanCancer genomic data, we then asked whether PLCD4, PLCB4 and PLD3 levels correlate to the pathogenesis of human pancreatic ductal carcinoma." (PMID 35255936, 2022).
prostate carcinoma (2 papers, 2017 to 2024). A carcinoma that arises from epithelial cells of the prostate gland. "PLCB4, which encodes a positive regulator of the phosphatidylinositol-3-kinase signaling pathway, has been implicated in prostate cancer." (PMID 38956663, 2024). "In human cancers, PLCB4 amplification has not been formally documented as a mechanism underlying overexpression, while it is provisionally catalogued in 20.6% of prostatic carcinomas exhibiting neuroendocrine phenotypes by the cBioPortal platform for cancer genomics." (PMID 28212550, 2017).
schizophrenia (2 papers, 2010 to 2022). A major psychotic disorder characterized by abnormalities in the perception or expression of reality. "We then focused on three genes; Myristoylated alanine-rich protein kinase C substrate (MARCKS), Phospholipase C beta 4 (PLCB4) and Synaptotagmin 1 (SYT1), because an accumulating number of reports point to the involvement of impaired neural transmission in the schizophrenia pathology." (PMID 20098743, 2010).
absence seizures (1 paper, 2014). "TC-limited knockdown as well as whole-animal knockout of PLCβ4 induced spontaneous SWDs with simultaneous behavioral arrests and increased the susceptibility to drug-induced SWDs, highlighting the role of thalamic PLCβ4 in the genesis of absence seizures." (PMID 25548594, 2014).